CD163 (CD163 molecule)
Diseases named in the same sentence as CD163 in open-access papers (continued):
Sharing a sentence is not in itself a finding about the gene and the disease.
tumor (continued). "Interestingly, in patients with a high NLR, peritumoral IL-17 levels and CD163-positive tumor-associated macrophages (TAMs) were significantly increased." (PMID 34638613, 2021). "In addition, the expression of SIRPA and macrophage markers (CD68 and CD163) in tumor-associated immune cells (TAIs) was analyzed." (PMID 33799989, 2021). "This may be relevant also in light of the observations herein, where down-regulation of CD163+ TAMs in Ndst1f/f CD11cCre+ mutants was also associated with a tumor phenotype showing reduction in FOXP3+ cells associated with tumors in mutant mice." (PMID 34715561, 2021). "Similarly, tumor-associated macrophages (TAMs) have been shown to predict an unfavorable prognosis, in particular, the M2-polarized (CD163+) subset." (PMID 32852603, 2021). "Interestingly, in the hrHPV+ subgroup (N = 43) high infiltration rates of CD68+ and CD163+ cells in the PT Tumor compartment were associated with LN metastasis (p = 0.031 and p = 0.026, respectively)." (PMID 34194435, 2021). "High numbers of CD68+ TAMs in the tumor stroma were significantly associated with larger tumor size and positive nodal metastasis, whereas high numbers of CD163+ TAMs in the tumor stroma were significantly associated with positive vascular invasion, nodal metastasis, and molecular subtypes." (PMID 33968034, 2021). "Moreover, we also explore the association between CD163 expression and gene markers of tumor-infiltrating immune cells." (PMID 34395626, 2021). "Proinflammatory M1 macrophages could phagocytose cancer cells, while anti-inflammatory CD163+ tumor-associated macrophages could promote tumor growth and invasion." (PMID 35155189, 2021). "The number of CD68+ tumor associated macrophages does not correlate with the prognosis of patients with EC, while high numbers of CD163+ macrophages in the tumor stroma may be associated with both low survival, later stage, and the presence of metastases." (PMID 34203319, 2021). "They found that a high number of nitric oxide synthase 2 (INOS+) M1-like macrophages, both inside the tumor and at the invasive margins, was significantly associated with better OS, whereas the presence of CD163+ M2-like macrophages, inside the tumor, showed a trend toward poor prognosis." (PMID 34944971, 2021). "High expression of GBE1 may promote high infiltration level of CD163+ tumor-associated macrophages in LUAD." (PMID 35155189, 2021). "Higher MACC1 mRNA levels were positively correlated with CD163+ tumor-associated macrophages (r = 0.614, p < 0.001), and were negatively correlated with CD56+ natural killer cells (r = −0.398, p < 0.001) and CD8+ cytotoxic T lymphocytes (r = −0.323, p < 0.001)." (PMID 34577857, 2021). "Besides, more CD163+ M2 tumor-associated macrophages (TAMs) were found to infiltrate into the tumor and adjacent stroma." (PMID 34795209, 2021). "This was also accompanied by a reduction in M2-type CD163+ tumor-associated cells in mutants." (PMID 34715561, 2021). "However, the density of M2-type tumor-associated macrophages with CD68+ CD163+ phenotypes was significantly higher (P < 0.01) in tumors from DPP-4i users." (PMID 36860286, 2021). "In one research, CD163 positive tumor-associated macrophages (TAM) may induce angiogenesis via crosstalk with malignant epithelial cells to promote Wnt5a expression." (PMID 33754039, 2021). "CD163 is a marker of tumor-associated macrophages with an M2 phenotype." (PMID 33968055, 2021). "Our results implied that expression of GBE1 may be related with CD163+ tumor-associated macrophage infiltration in LUAD." (PMID 35155189, 2021). "IDO-positive tumors contained significantly higher amounts of FoxP3+ Tregs (p < 0.0001), IDO+ stromal immune cells (p < 0.0001), and both CD68+ and CD163+ tumor associated macrophages (TAMs) (p-values < 0.0001), compared to IDO-negative tumors (data not shown)." (PMID 34051744, 2021). "Moreover, GBE1 was positively correlated with infiltrating levels of CD163+ tumor-associated macrophages in LUAD." (PMID 35155189, 2021).
tumor (continued). "In addition, the tumor-associated CD163+ macrophages expressed indoleamine-pyrrole 2,3-dioxygenase (IDO1), reaching again 73% in UPSs." (PMID 33478080, 2021). "Furthermore, we verified the relationship between GBE1 expression and CD163+ tumor-associated macrophages via IHC staining." (PMID 35155189, 2021). "CD163 is a marker of M2 type tumor-associated macrophage (TAM)." (PMID 33154945, 2020). "Moreover, infiltration of both CD68+ and CD163+ TAMs was also significantly associated with high tumor expression of PD-L1." (PMID 32630659, 2020). "Other possible mechanisms underlying HPD could be linked to tumor-infiltration by M2-like CD163+CD33+PD-L1+ clustered epithelioid macrophages or to specific gene expression signatures." (PMID 36046388, 2020). "The correlation between LGALS3 expression and the infiltration of multiple intra-tumoral immune cell types, including B cells (CD20), T cells (CD4 and CD8), macrophages (CD68), and M2 tumor-associated macrophages (CD163), was evaluated by Spearman correlation analysis." (PMID 32528967, 2020). "Moreover, CD163+/CD68+ ratio in tumor front was also significantly associated with EMT program and CTC amount." (PMID 33194645, 2020). "The immune infiltrate was characterized by the presence of CD3+ cells (T-cells) and CD163+ cells (M2-like tumor associated macrophages, M2-TAMs), regarded as immunosuppressive and pro-tumoral cells, and FoxP3+ cells (activated T regulatory cells, Treg) in serial and consecutive sections." (PMID 32899203, 2020). "CD163+ TAMs in TCA were associated with the formation of multiple tumour nodules (p = 0.016)." (PMID 31170995, 2019). "Furthermore, near tumor invasive front, high level of CD163 was associated with less E-cadherin and more Vimentin, an indication of EMT." (PMID 30927925, 2019). "Indeed, we and others have shown that in vitro tumor-conditioned tumor-associated macrophages (TAMs) exhibit a mixed M1/M2 macrophage phenotype, expressing both M2 (CD163 and CD206) and M1 (IL-1β, IL-6, TNF-α, and CCL3) markers." (PMID 30917934, 2019). "Compared to low CD163+ macrophage populations, the high CD163+ counts were associated with higher pT-stage (p = 0.015) and the trend towards larger tumor diameter (p = 0.058)." (PMID 31771616, 2019). "HHLA2 overexpression was associated with sparser CD3+ tumor infiltrating lymphocytes (TILs), CD8+ TILs and a higher CD4 + Foxp3+/CD8+ TIL ratio, whereas PD-L1 expression was associated with prominent T cells and CD163+ tumor associated macrophages infiltrations." (PMID 30885276, 2019). "Of note, in a subset of patients PD-L1 expression in tumor cells was significantly associated with “M2”-like macrophage phenotype (driven by the expression of CD163) while both PD-L1 and “M2”-like macrophages were associated with higher Ki67 expression and tumor grade." (PMID 31581535, 2019). "Moreover, high numbers of CD68+ M and CD163+ M2 cells within the tumor were significantly associated with worse OS (HR = 1.892, 1.845; p = 0.009, 0.012)." (PMID 31771616, 2019). "Tumor-associated macrophages (TAMs) promote tumor progression and inhibit anti-tumor immune response by producing various mediators and preferentially express CD163, CD204, and CD206." (PMID 31601953, 2019). "The positive CD163 labeling of OPA-associated macrophages therefore suggests that these cells might also promote tumor growth in OPA." (PMID 31434729, 2019). "Notably, reduced number of Iba1- and CD163-positive tumor-associated macrophages (TAMs) was observed in xenografts derived from miR-125 agomir-treated tumor cells." (PMID 30237497, 2018). "As we can see, the treatment of asialyl-agalactosyl IgG did not change an expression of a general macrophage marker CD68 but increased mRNA and protein levels of tumor-associated macrophage markers CD163 and CD204 in both macrophagic U-937 cells and human peripheral macrophages at day six." (PMID 30469416, 2018). "CD163+ tumor-associated macrophages (TAMs) were the dominant population." (PMID 30400835, 2018).
tumor (continued). "CD163+ macrophages in tumor regions are also referred to as tumor associated macrophages (TAM)." (PMID 30619287, 2018). "Therefore, the association between M2 CD163+ TIMs and tumour response to NAC in both the breast and ALNs was examined." (PMID 28913366, 2017). "Strikingly, there were a large numbers of infiltrated CD163 positive macrophages in these metastatic lymph nodes, indicating CD163 positive macrophages might be the key cause of tumor immune evasion in lymph nodes." (PMID 29152078, 2017). "CD163 has been used as both a tumor-associated and M2 macrophage marker, CD169 has been used as a marker of subsets of macrophages in lymph nodes, lung, and GI tract independent of the M1/M2 classification system, and CD206 has been used as a general M2 marker." (PMID 28619036, 2017). "The levels of CD163 expression in tumor cells were positively associated with the expression of E-cadherin (P = 0.04 and P = 0.038, respectively) and vimentin (P < 0.001 and P < 0.001, respectively) in tumors and at the tumor invasion front." (PMID 26769084, 2016). "Macrophages can be classically activated into M1 cells that express inducible nitric oxidase (iNOS), IL-12 and high levels of co-stimulator molecules while resident tissue macrophages and tumor-associated macrophages are likely to express CD163, 206, arginase and IL-10, a M2 phenotype." (PMID 26509874, 2015). "Recently, the same authors demonstrated that the inclusion of 5 inflammation related genes increased the predictive power of the gene signature, since tumors from high-risk NB patients present a greater infiltration of CD163+, M2-type, tumor associated macrophages (TAMs)." (PMID 26161395, 2015). "CD163 expression was associated with advanced tumor stages and poor prognosis." (PMID 26585897, 2015). "CD163+ tumor-associated macrophages (TAMs) play an important role in the progression of cancer." (PMID 25871392, 2015). "CD163+ MΦ, in contrast, were associated with inferior survival and might actively be induced and maintained by the tumor cells." (PMID 25470820, 2014). "The presence of IL13 and M-CSF in cHL cases might be responsible for the induction of MΦ-2-like CD163+ tumor-associated macrophages in cHL, whereas IL4 was detected infrequently and, if at all, seems to play a minor role." (PMID 25470820, 2014). "Indeed, the IL-10-conditioned CD14+ DDC with a DC-SIGN+BDCA3+CD163+ phenotype are highly reminiscent of both tumor-associated macrophages and DC, adopting similar M2-like immunosuppressive traits." (PMID 23875023, 2013). "CD163 is strongly expressed in “tumour-associated macrophages” and in a number of cancer types its expression is associated with survival, reflecting the tumour supportive nature of tumour-associated macrophages." (PMID 23339669, 2013). "One study reported that CD163 may be down-regulated by the T-helper immune response in synovial tissues, suggesting that it may be underrepresented in tumor associated macrophages." (PMID 22289504, 2012). "CD163 was selected as the stratifying marker in this study due to its well-established role as a highly specific marker for M2-polarized tumor-associated macrophages, which play pivotal roles in immunosuppression, tumor progression, and metastatic dissemination." (PMID 41575920, 2026). "Moreover, the CD68+CD163+-CLS has been reported to exist in adipose tissue around BC lesions, and a high level of CD163+ macrophages (tumor-associated macrophages [TAMs]) was linked to shorter DFS (disease-free survival) in node-negative BC patients (P = 0.033)." (PMID 41255573, 2025). "Notably, residential macrophages, as identified through our single-cell analysis, were found to be upregulated in SCLC but were predominantly associated with the tumor-surrounding stroma, as evidenced by higher levels of CD163 and CD80 present in the immune stroma." (PMID 39231924, 2024).
tumor (continued). "Together, the data suggest that T98G-monocyte interactions result in differentiation of tumor-associated myeloid cells with high expression of CD163 and hampered potential to secrete cytokines, which could partly be rescued by the removal of sialic acid expression on the T98G cells." (PMID 39065651, 2024). "However, studies have shown varying degrees of expression of the surface receptors CD68 and CD163, utilized by these studies in their quantification of tumor‐associated macrophages in non‐macrophage cell types such as monocytes, dendritic cells, and neutrophils as well as in non‐immune cells." (PMID 38426622, 2024). "Building on this understanding, we postulated that HMOX1 expression within a comprehensive tumor gene expression data set could serve as a marker for investigating the influence of microhemorrhage on the development of CD163+ and SPP1+ TAMs, which are implicated in tumor progression." (PMID 38060331, 2023). "Thus, in a mouse model of sarcoma, tumor growth was abrogated in CD163 deficient mice." (PMID 34771453, 2021). "Hence, we used CD68 in combination with CD163 (M2 marker) to show tumor-associated macrophages." (PMID 33061855, 2020). "The phenotype of CD163+ cells is known to resemble alternatively activated, anti-inflammatory M2 macrophages, and several clinicopathologic studies of cancer have demonstrated that CD163+ macrophages are associated with tumor growth/progression and a worse prognosis." (PMID 32034190, 2020). "As CD206+ and CD163+ M2-like tumor-associated macrophages have been associated with tumor progression and poor clinical prognosis, we also verified whether magnolol increases M2-like tumor associated macrophages." (PMID 32117241, 2020). "Furthermore, MGL co-localization could be observed on a subset of the CD163+ tumor-associated myeloid cells." (PMID 30761272, 2019). "Furthermore, the presence of CD163+ TAMs was associated with a higher tumor MVD (ρ < 0.05)." (PMID 30038715, 2018). "Besides, CD163 expression was also associated with tumor invasion (p<0.01)." (PMID 29152078, 2017). "Importantly, the density of CD163-positive macrophages in tumor nest was significantly associated with the sex (P = 0.037) and mortality (P = 0.044), while that in the tumor stroma was significantly correlated with the recurrence (P = 0.008) and mortality (P = 0.04)." (PMID 26769084, 2016). "Serum IL-22 levels were measured by ELISA, and the density of CD163+ cells in the tumor tissue was analyzed immunohistochemically." (PMID 41752653, 2026). "Immune markers, such as CD47, CD163, and B7-H3, play crucial roles in tumor immune evasion and macrophage polarization." (PMID 42075550, 2026). "Tumor stage stratification revealed that TAMs, especially CD163+, were more abundant in TIM of T3 tumors, whereas CD80+ macrophages predominated in less invasive T1 tumors." (PMID 41438574, 2026). "M2 macrophages were identified by CD163 staining, and quantification of CD163+ cells within the tumor microenvironment demonstrated a significant positive correlation between BGN protein expression and M2 macrophage infiltration (R = 0.494, P < 0.001)." (PMID 41328346, 2026). "Tumor-associated macrophages (TAMs) in ccRCC are abundant and phenotypically diverse, with CD68 marking general macrophage presence and CD163 indicating alternatively activated, immunosuppressive (M2-like) subsets." (PMID 41846920, 2026). "Among nine patients with matched pre- and post-immunotherapy samples, TAMs density significantly increased post-treatment (p = 0.01 and p = 0.03), with CD163 + macrophages clustering at the tumor periphery in 78% of cases." (PMID 41591510, 2026). "Inflammation in the tumor microenvironment, including the presence of immunosuppressive M2-macrophages (CD163+), plays a key role in disease progression." (PMID 41752653, 2026).
tumor (continued). "In contrast, the high-risk group exhibited stronger co-localization of immunosuppressive tumor-associated macrophages and neutrophils (CD66b+/MMP9+ and CD163+/MMP9+)." (PMID 41491099, 2026). "In vivo, METTL3 knockdown significantly attenuated subcutaneous tumor growth in nude mice (p < 0.05) and reduced PD-L1 and CD163 expression (p < 0.05)." (PMID 42064710, 2026). "Macrophages not only promote tumor proliferation and invasion but also play a significant role in tumor immunotherapy, especially CD163, a molecule that specifically marks macrophages, especially M2 macrophages." (PMID 41575920, 2026). "In both genotypes (WT and KO) and treatment groups (Veh and Bc), CD163+ Toe-Macs were detected within tumor regions expressing high levels of NLRP3, IL-1β, TGF-β1, CCL2, IL-6, and PD-L1." (PMID 40794443, 2025). "Complementary in vivo assays substantiate that RP-6306, either as monotherapy or in synergy with gemcitabine, significantly escalates CD86 levels while diminishing CD163 expression in tumor matrices." (PMID 40664640, 2025). "Cd163 expression was reduced in tumor macrophages and showed relative increases after drug treatment." (PMID 40992926, 2025). "A lower degree of infiltration of CD163+ macrophages occurred in both tumor and total in the Io+Chemo versus Chemo (density: tumor, p=0.001, total, p=0.018; percentage: tumor, p=0.003, total, p=0.004; H-score: tumor, p=0.000, total, p=0.007)." (PMID 39931056, 2025). "In FGFR2+ TMEs, we confirmed that the node in the network associated with tumor cells was generally distant from the CD8+ T-cell effector immune cell types and near CD11b+/CD15+ granulocytes and CD68+/CD163+ macrophages." (PMID 39969434, 2025). "A similar association with a gradual increase of infiltration by TILs, TAMs, CD8, CD68 as well as the CD68/CD163 ratio was observed for tumour size (pTis →pT1→pT2)." (PMID 41018083, 2025). "The analysis of the gene signature revealed strong positive correlations with multiple immune checkpoints, including HAVCR2, IL10RA, CSF1R, and CD163, suggesting these genes play a role in regulating the immunosuppressive tumor microenvironment." (PMID 40507280, 2025). "The expression patterns of CD68, CD86, and CD163 were first analyzed to assess differences between the tumor nest and tumor stroma." (PMID 40510346, 2025). "We observed elevated CD206 and CD163 levels in macrophages cocultured with C1q‐treated tumor cells compared to controls, while Azacitidine treatment abolished the effect of tumor cells to promote macrophage M2 phenotype transition." (PMID 40171991, 2025). "H&E and IHC revealed that the protein levels of IRF9 and CD163 were greater in the tumor tissues from the ITGβ8‐overexpressing group than in those from the control group." (PMID 39535362, 2025). "Our clinical data also confirms that elevated levels of CD163+ macrophages with reduced levels of CD8+ infiltration into the tumours result in worse overall survival." (PMID 39915477, 2025). "CD163-positive cells, which can have both pro- and anti-tumor activity, increased in the EX+MNU group, indicating changes in immune responses and tissue remodeling, as demonstrated by double immunostaining." (PMID 40284805, 2025). "Decrease of M2 macrophages within the tumor by Akt inhibitor, even when combined with RT + αPD-L1/αCTLA-4, was further supported by a reduction in CD163 expression in immunohistochemistry (IHC) staining." (PMID 41378083, 2025). "To test this, we performed immunohistochemistry against CD163, a putative M2-polarisation marker and TREM2, a protein associated with immunosuppressive activity in tumour-associated microglia/macrophages." (PMID 39948623, 2025). "We demonstrated that VS-induced SNHL was linked to increased secretion of TNF-α, IL-2R, CD163, eotaxin, and HGF, while larger tumor size was associated with higher levels of TNF-α, TNF-R2, IL-1α, IFN-α, MIP-1β, and IL-21 secretion." (PMID 39923035, 2025).